IL27 (interleukin 27)
Diseases named in the same sentence as IL27 in open-access papers (continued):
Sharing a sentence is not in itself a finding about the gene and the disease.
tumor (continued). "In spite of well-documented antitumor activities for IL-27, tumor promoting effects have been reported for this cytokine, as well." (PMID 30581461, 2018). "Other studies have suggested that IL-27 exerts some of its tumor promoting effects through induction of immune regulatory phenotypes, such as increasing the expression of molecules like IL-18BP, PD-L1/2, IDO, CD39, Tim3, and IL-10." (PMID 30581461, 2018). "Among cytokines being investigated for probable therapeutic applications, IL-27 has been shown to have both tumor promoting and suppressing functions, depending on the characteristics of the target neoplasm." (PMID 30581461, 2018). "IL-27 produced by DCs is necessary for trafficking of Tregs to locate in tumor, and pulmonary CD1c+ DC-mediated development of Tregs is dependent on IL-27/IL-10/inducible costimulator ligand." (PMID 30483251, 2018). "In view of its immune-enhancing activities and direct anti-tumor effects IL-27 has been considered as a potential anti-tumor agent." (PMID 29020964, 2017). "Our data show that TTP suppresses CD8+ T-cell function by inhibiting IL-27 production, resulting in acceleration of tumor growth." (PMID 29021521, 2017). "IL-27 therapy inhibited the growth of NK-resistant head and neck squamous carcinoma cells in syngeneic mice through the induction of an anti-tumor IgG antibody response and NK-mediated antibody-dependent cellular cytotoxicity." (PMID 28255204, 2017). "Other researchers have confirmed that IL-27 exhibits anticancer activity towards different tumours through several mechanisms, such as through the stimulation of NK cells and the CTL response, as well as the suppression of angiogenesis." (PMID 29089667, 2017). "Soluble molecules include cytokines with immunosuppressive activity, such as IL-10, transforming growth factor (TGF)-β, and IL-27, which regulate immune responses to tumor cells and induce T cell dysfunction within the tumor microenvironment." (PMID 28545567, 2017). "IL-27 can act through multiple mechanisms such as activation of antitumor immune responses and direct inhibition of tumor cell proliferation, survival, and angiogenic and invasive properties." (PMID 28255204, 2017). "Mice that eventually rejected IL-27-expressing cells developed immunity to tumor antigens as demonstrated by rechallenge experiments with wild-type tumor cells." (PMID 28255204, 2017). "These include IL-27 that is of interest in tumor immunology because it combines immunostimulatory and anti-angiogenic properties." (PMID 28456791, 2017). "Recently, IL-27 was proven to possess multifaceted anti-tumor activity in lung, prostate, pancreatic and breast cancers." (PMID 28746469, 2017). "In recent studies, it has been demonstrated that the immunosuppressive cytokine, IL-27, is a potent inducer of Tim-3+ exhausted/dysfunctional T cells and a promoter of tumor growth in mice model." (PMID 28545567, 2017). "Altogether immune-stimulatory activities and direct anti-tumor effects support the possible usage of IL-27 for tumor therapy." (PMID 27683036, 2016). "One prominent question is mechanistically how IL27 signaling through CD11b-positive cells affects angiogenesis and tumor formation." (PMID 27738312, 2016). "The observation that IL27 promotes skin angiogenesis via ETAR provoked further investigation into the effect of the premalignant niche on tumor initiation and growth." (PMID 27738312, 2016). "A key finding of this study is the tumor promoter activity of IL27 in the skin, and this discovery is surprising given that previous studies have attributed to IL27 anti-tumor activities mainly via eliciting an anti-immune response." (PMID 27738312, 2016). "Considering that IL27 promoted tumor initiation in this skin model, we sought to determine how angiogenesis was also affected." (PMID 27738312, 2016).
tumor (continued). "The observation that mice are resistant to cutaneous skin carcinogenesis upon deletion of IL27RA in hematopoietic compartment suggests that most likely IL27 signaling through these cells is needed to promote tumor growth and angiogenesis." (PMID 27738312, 2016). "Previous in vivo studies have suggested the antitumor activities of IL-27 in animal models, whereas clinical observations indicate the link of IL-27 in tumor progression." (PMID 27119567, 2016). "IL-27, a member of the IL-12-family of cytokines, has shown anti-tumor activity in several pre-clinical models due to anti-proliferative, anti-angiogenic and immune-enhancing effects." (PMID 27683036, 2016). "Since IL27 can signal through multiple cell types including myeloid cells, comparing the activity of IL27 in the DMBA/BP skin carcinogenesis protocol in CD11b−/− with wild type (WT) mice would reveal the roles of these cell types." (PMID 27738312, 2016). "IL-27 functions as a pleiotropic cytokine that is capable of modulating immune response, inflammation, hematopoiesis, and tumor growth." (PMID 27119567, 2016). "A growing body of evidence has validated the protective role of physiological levels of IL-27 against the development and progression of carcinogen- and transgene-driven neoplasms." (PMID 26014498, 2015). "IL-27 inhibits the growth and invasiveness of different cancers and therefore represents a potential anti-tumor agent." (PMID 26657115, 2015). "On the other hand, IL-27 exerts potent antitumor effects against various tumor models via different mechanisms, depending on the characteristic of each tumor." (PMID 25969628, 2015). "In mouse tumor model, such as colon cancer, IL-27 strengthens anti-tumor activity by supporting production of perforin and granzyme B from CD8+ T cells, in addition to the promotion of proliferation and IFN-γ production." (PMID 25633106, 2015). "Interleukin-27 (IL-27), a heterodimeric cytokine belonging to the IL-12 family, not only act on hepatocytes against viral activity but also curb tumor proliferation." (PMID 25908103, 2015). "In vivo, IL-27 hampered both AC and SCC tumor growth in association with a prominent granulocyte- and macrophage-driven colliquative necrosis, CXCL3 production, and a reduced pluripotency- and EMT-related gene expression." (PMID 25638163, 2015). "The only pro-angiogenic genes found up-regulated, and substantially, were that coding the chemokine IP-10/CXCL10 which was also strongly expressed in vivo by PC3 tumor from IL-27 treated animals, and the metalloproteinase inhibitor, TIMP3, in DU145 cells." (PMID 24681516, 2014). "Consistently, in vivo studies using the DU145 cells revealed a significant and more rapid inhibition of tumor growth by IL-27 treatment than that observed using the PC3 cells." (PMID 24681516, 2014). "In the present paper, we develop a mathematical model that describes the anti-tumor activity of CD8+ T cells in terms of IFN- and IL-10 productions, when these T cells are activated by IL-27 from the tumor microenvironment." (PMID 24633175, 2014). "On the other hand Interleukin-27 inhibits the secretion of Interferon- by CD8+ T cells which somewhat diminishes the inhibition of tumor growth." (PMID 24633175, 2014). "Simulations of the model show how Interleukin-27 promotes CD8+ T cells to secrete Interleukin-10 to inhibit tumor growth." (PMID 24633175, 2014). "In contrast, IL-12 and IL-27 act as inhibitors of Th2 type responses and play key roles in anti-tumor immune responses." (PMID 25031487, 2014). "The recently identified heterodimeric member of the IL-6/IL-12 family of cytokines namely interleukin (IL)-27, has revealed potent anti-tumor effects in various tumor models and, importantly, freedom from toxicity in preclinical trials." (PMID 24681516, 2014). "In vivo studies revealed that IL-27 hampered PC3 tumor growth in athymic nude mice and significantly reduced tumor volume after more than one month of treatment." (PMID 24681516, 2014).
tumor (continued). "In recent years there has been increasing interest to investigate the role of another member of the IL-12 family, namely, Interleukin-27 (IL-27), which is less toxic than IL-12, as a potential anti-tumor agent." (PMID 24633175, 2014). "Conversely, positive PRCC means that increased rejection of the tumor (treated by IL-27 versus untreated) will occur if this parameter is decreased." (PMID 24633175, 2014). "They found that IL-27 significantly enhances the survival of activated tumor antigen specific CD8+ T cells in vitro and in vivo, and induces IL-10 upregulation in these T cells." (PMID 24633175, 2014). "We note in particular that pro-inflammatory macrophages secrete a family of IL-12 cytokines including IL-27, and the IL-12 family attracts CTLs which kill tumor cells, so that macrophages suppress tumor growth." (PMID 24633175, 2014). "The lack of toxicity revealed in preclinical trials along with the powerful anti-cancer effects demonstrated in different tumor types have driven our attempt to explore IL-27 as a candidate anti-PCa agent." (PMID 24681516, 2014). "Positivity for IL-27 in tumor cells was observed in 2/8 cases of stage 1, 7/12 cases of stage 2, 10/12 cases of stage 3, and 9/11 cases of stage 4." (PMID 24130734, 2013). "Of note, the combination of IL-27 and poly(I:C) significantly inhibited tumor progression compared with PBS alone." (PMID 24155891, 2013). "In summary, these data demonstrate the physiological importance of IL-27 signals during immunosurveillance and anti-tumor responses in mouse models of cancer." (PMID 23554861, 2013). "IL-27 has attracted interest as an anti-tumor agent because of its similarities to IL-12, which also demonstrated ability to suppress tumor growth and elicit tumor specific immune responses." (PMID 24274066, 2013). "Strategies testing rIL-23 overexpression in tumor cells resulted in enhanced anti-tumor responses and inhibited cancer progression, analogous to IL-12 and IL-27." (PMID 23554861, 2013). "Although IL-27 has been shown to have potent anti-tumor activity in various cancer models, the role of IL-27 in EMT and angiogenesis is poorly understood." (PMID 24274066, 2013). "In preclinical models, IL-27 has been shown to have anti-tumor properties in a variety of malignancies through several mechanisms, including inhibition of tumor proliferation and angiogenesis." (PMID 24274066, 2013). "We and other groups previously reported that IL-27 has a potent ability to induce tumor-specific antitumor and protective immunity through cytotoxic T lymphocyte (CTL) and natural killer (NK) cells in colon carcinoma colon 26 and neuroblastoma TBJ lines." (PMID 24155891, 2013). "In each case, however, these studies have relied on transplanted cell line models and most have used forced expression of recombinant IL-27, or its receptor, ectopically in tumor cells lines." (PMID 23554861, 2013). "Our data demonstrate that IL-27 signaling enhances the anti-tumor immune response during in vivo development and growth of two diverse tumor types." (PMID 23554861, 2013). "This is the first report to show a role for TRAIL in IL-27–mediated inhibition of tumor growth as well as a cooperative effect between IL-27 and poly(I:C) on the inhibition of tumor growth through TLR3 up-regulation by IL-27." (PMID 24155891, 2013). "Analysis of the effects of physiological IL-27 signaling on endogenously arising, heterogeneous tumors is required to properly assess the anti-tumor potential of this cytokine." (PMID 23554861, 2013). "Together, these two models provide strong evidence for an important role for IL-27 signals in promoting anti-tumor immunity against de novo tumors." (PMID 23554861, 2013). "Consistent with this proposition, a number of reports have suggested that IL-27 can promote anti-tumor cell line immune responses." (PMID 23554861, 2013). "Our data suggest that IL-27 signals are indispensable for IFN-γ production by CD4+ T cells in tumor immunity." (PMID 23554861, 2013).
tumor (continued). "The early tumor induction observed in Il27ra−/− mice in both cancer models suggests that IL-27 signals play an important role in immunosurveillance during neoplasia." (PMID 23554861, 2013). "Although the anti-tumor properties of IL-27 have been described previously, our study describes a new mechanism by which IL-27 inhibits EMT and angiogenesis through a STAT1 dominant pathway." (PMID 24274066, 2013). "We previously demonstrated that IL-27 inhibits the tumor growth of B16F10-WSX-1 cells through the WSX-1/STAT1 and IRF-1 pathway." (PMID 24155891, 2013). "We analyzed the in situ expression of IL-27 in melanocytic lesions (n = 82) representative of different stages of tumor progression." (PMID 24130734, 2013). "Neutralizing antibody against TRAIL partly but significantly blocked the IL-27–mediated inhibition of tumor growth." (PMID 24155891, 2013). "Then, the involvement of up-regulated sensors for poly(I:C) in inhibiting SK-MEL-37 tumor growth by combining IL-27 and ploy(I:C) was investigated by knock-down of their expression using respective siRNAs." (PMID 24155891, 2013). "In this study, we investigated the in situ expression of IL-27 in melanocytic lesions representative of different stages of tumor progression." (PMID 24130734, 2013). "While many studies have investigated the role of ectopic expression of IL-27 in murine tumor models, little is known on the role of endogenous IL-27/IL-27R in the development of human tumors." (PMID 24130734, 2013). "One possibility is that tumors overexpressing WSX1 compete with immune cells for IL27 and reduce the bioavailability of IL27 to signal into immune cells since IL27 generates anti-tumor activities via signaling through host immune cells." (PMID 21559505, 2011). "Previous studies have shown that IL-27 expressing tumors decrease tumor volume by enhancing NK and CTL activity and inhibiting COX-2 expression." (PMID 21559505, 2011). "But, if IL27 signals in tumor cells and inhibits tumor growth, then why do tumor cells that overexpress WSX1 grow faster than GFP control?" (PMID 21559505, 2011). "To determine the dependency of WSX1 promotion of tumor growth on IL27 signaling, we first assessed tumor growth differences between LLC cells expressing full-length WSX1 (LLC-WSX1) and WSX1-Mutant (LLC-MUT, lacking intracellular domain including Box1 domain)." (PMID 21559505, 2011). "In contrast, other studies in conjunction to this study have shown that WSX1-expressing tumors can either promote or inhibit tumor growth independently of IL27." (PMID 21559505, 2011). "IL-12, a prototype member of a family of IL-12-related cytokines that includes IL-23 and IL-27, is an instigator of Th1 immune responses and possesses in vivo anti-tumor activities." (PMID 21062439, 2010). "IL-27 not only activates NK cells but also induces tumor-specific immunoglobulin that cooperatively elicit ADCC activity." (PMID 20885915, 2010). "B16F10 cells transfected with IL-27 gene not only markedly suppress tumor-induced neovascularization in lung metastases but also clearly inhibit angiogenesis." (PMID 20885915, 2010). "For instance, highly immunogenic murine colon carcinoma Colon 26 cells transfected with the IL-27 expression vector showed greatly reduced tumor growth, which is mainly mediated by CD8+ T cells, IFN-γ and T-bet." (PMID 20885915, 2010). "B16F10 cells transfected with IL-27 gene exert antitumor activity against subcutaneous tumor and also experimental pulmonary metastasis even in IFN-γ-deficient mice." (PMID 20885915, 2010). "Endogenous IL-27 was revealed to promote tumor-specific CTL generation in CD8+ T cells, while suppressing APC function in DCs, during generation of tumor immunity." (PMID 20885915, 2010). "In mouse models also IL-27 had a strong anti-tumor effect, which was enhanced by the presence of IL-12." (PMID 19798410, 2009).
tumor (continued). "Conversely, IL-27R agonism through hydrodynamic tail vein injection of IL-27-encoding plasmid resulted in complete tumor control without relevant toxicity, a common side effect associated with cytokine-based therapies." (PMID 40254608, 2025). "However, IL-27 can also induce the production of immunosuppressive cytokines, such as IL-10, which dampen anti-tumor immune responses." (PMID 41254398, 2025). "Their findings reveal that IL-27 enhances the persistence and effector functions of tumor-infiltrating CD8+ T lymphocytes (TILs), preventing exhaustion, sustaining T cell-dependent tumor control and immunotherapy efficacy without significant systemic side effects." (PMID 40254608, 2025). "However, in less inflammatory settings, such as tumor growth, the overexpression of IL-27 resulted in LSK expansion and the induction of an M1 macrophage population." (PMID 39868131, 2025). "EBI3 may contribute to the anti-tumor effects of IL-27, though further research and clinical validation are required to determine its specific applications in tumor immunotherapy." (PMID 40519922, 2025). "This cytokine can promote tumor growth and progression under certain conditions by stimulating the production of other inflammatory cytokines and chemokines, including interleukin-17 (IL-17), IL-6, and IL-27." (PMID 41254398, 2025). "IL-27 ectopic expression completely reshaped the TME by promoting overall and RPL18-specific CTL infiltration in the tumor, as well as enhancing their cytotoxic activity, as demonstrated by IL-27-dependent upregulation of Ki-67, granzyme B, PD1, CD39, and SCA1 markers." (PMID 40254608, 2025). "Considering the significant anti-tumor and pro-osteogenic effects of IL-27 and cabo combination therapy, RNA-sequencing was used to further elucidate the mechanisms contributing to the therapeutic effects of these agents utilizing an in vivo intratibial TC2Ras model." (PMID 37842640, 2023). "This was due to enhanced production of IL-27 by macrophages in the tumor microenvironment." (PMID 38274271, 2023). "Many in vivo studies have demonstrated the anti-tumor effects of endogenous and exogenous IL-27." (PMID 37842640, 2023). "We hypothesized that the combination of IL-27 and cabo could enhance the immunogenicity of the tumor microenvironment, have potent anti-tumor effects, and improve bone quality." (PMID 37842640, 2023). "Overall, IL-27 and cabo work together to increase the infiltration of anti-tumor immune cell types, decrease the presence of immune-suppressive regulatory immune cells, and inhibit angiogenesis in the tumor." (PMID 37842640, 2023). "Of particular importance, patient-derived T cells treated with IL-27 displayed a higher cytotoxic ability toward leukemic cells than their untreated counterparts; highlighting the potential of this cytokine to reactivate anti-tumor immunity in CLL patients." (PMID 37937211, 2023). "The co-recruitment of IDO and PD-L1 in tumor cells is also produced by IL-27, which may indicate redundancy in this activity, important to host survival, or possible synergism between them to maximize their anti-tumor potential." (PMID 37296860, 2023). "The decrease in tumor load was accompanied by the partial restauration of the anti-tumor immune response, evidenced by a less immunosuppressive leukemic immune landscape in the presence of IL-27, and in consonance with our previous publications." (PMID 37937211, 2023). "It was hypothesized that the combination of IL-27 gene therapy and cabo could improve the immunogenicity of the tumor microenvironment, synergizing their anti-tumor effects while improving overall bone quality." (PMID 37842640, 2023). "The suppression of mast cells by IL-27 and cabo treatment may have the potential to inhibit metastatic tumor growth." (PMID 37842640, 2023). "Furthermore, STAT1 phosphorylation was found to be indispensable for IFN-γ- and IL-27-induced PD-L1 expression on tumor cells and monocytes." (PMID 37131151, 2023).